TMEM132B (transmembrane protein 132B)
Synonyms: KIAA1786; KIAA1906
Tractability: Antibody: UniProt predicts a signal peptide or a membrane-spanning region. PROTAC: ubiquitination databases record sites on it; its protein half-life has been measured.
Gene: Protein-coding gene on chromosome 12 (125,186,386 to 125,662,377, forward strand). Ensembl gene ENSG00000139364.
Subcellular location: Membrane
Gene Ontology:
Cellular component: membrane
Genetic constraint (gnomAD): Loss-of-function variants: 18 observed, 92.76 expected, observed/expected ratio (o/e) 0.19, 90% interval 0.13 to 0.29. The upper end of that interval is the gene's LOEUF score, 0.29, which puts it in group 1 of 6, group 1 being the genes least tolerant of losing a copy. Missense variants: 1,093 observed, 1,377.5 expected, observed/expected ratio (o/e) 0.79, 90% interval 0.75 to 0.83. Synonymous variants: 500 observed, 545.06 expected, observed/expected ratio (o/e) 0.92, 90% interval 0.85 to 0.99.
Homologues: Orthologues: chimpanzee TMEM132B (98% identical), macaque TMEM132B (97% identical), dog TMEM132B (87% identical), mouse Tmem132b (86% identical), rat Tmem132b (86% identical), guinea pig TMEM132B (84% identical), pig TMEM132B (84% identical), rabbit TMEM132B (84% identical), tropical clawed frog tmem132b (62% identical), zebrafish si:dkey-1d7.3 (35% identical), Drosophila melanogaster dtn (25% identical), Caenorhabditis elegans tmem-132 (17% identical). Paralogues in human: TMEM132C (53% identical), TMEM132D (51% identical), TMEM132E (35% identical), TMEM132A (30% identical).
Diseases named in the same sentence as TMEM132B in open-access papers:
TMEM132B is named in the same sentence as 7 diseases in open-access papers, as found by Europe PMC text mining. Sharing a sentence is not in itself a finding about the gene and the disease. The quoted sentences say what the papers report.
aneurysm (1 paper, 2021). Bulging or ballooning in an area of an artery secondary to arterial wall weakening. "Peripheral blood TMEM132B mRNA expression was previously found to differ significantly between aneurysm patients and controls." (PMID 33971621, 2021). "Aneurysms are known to be caused by immune illnesses, infections, acute or blunt injuries and atherosclerosis; thus, the alteration of TMEM132B in both MDD and aneurysm patients suggests that MDD is also linked to immunity and inflammation." (PMID 33971621, 2021).
breast carcinoma (1 paper, 2024). "In breast cancer, TMEM132B is associated with poor prognosis and worse clinical outcomes." (PMID 39409914, 2024). "In-depth research is required to explore the roles of TMEM132B and GNB1L in breast cancer progression, especially their involvement in pathways related to tumor invasion and metastasis." (PMID 39409914, 2024). "Both TMEM132B and GNB1L have been reported to take part in breast cancer development and progression." (PMID 39409914, 2024). "Our analysis suggests that dysregulated activation of TMEM132B or GNB1L may contribute to worse progression, which was particularly prominent in Black breast cancer participants." (PMID 39409914, 2024).
tumor (1 paper, 2024). "Studies have shown that TMEM132B expression can be altered in tumor tissues compared to adjacent healthy tissues." (PMID 39409914, 2024).
TMEM132B also shares sentences with these, for which no sentence is quoted: atherosclerosis (1 paper); depression (1); diabetes (1); type 2 diabetes (1).